PLCG1 (phospholipase C gamma 1)
Description:
Mediates the production of the second messenger molecules diacylglycerol (DAG) and inositol 1,4,5-trisphosphate (IP3). Plays an important role in the regulation of intracellular signaling cascades. Becomes activated in response to ligand-mediated activation of receptor-type tyrosine kinases, such as PDGFRA, PDGFRB, EGFR, FGFR1, FGFR2, FGFR3 and FGFR4 (By similarity). Plays a role in actin reorganization and cell migration. Guanine nucleotide exchange factor that binds the GTPase DNM1 and catalyzes the dissociation of GDP, allowing a GTP molecule to bind in its place, therefore enhancing DNM1-dependent endocytosis (By similarity).
Synonyms: PLC-II; PLC1; PLC148; PLCgamma1; NCKAP3; IDAA
Tractability: Small molecule: a high-quality ligand is known. Antibody: its Gene Ontology location is reachable by antibodies, with high confidence; the Human Protein Atlas places it where antibodies can reach. PROTAC: UniProt records ubiquitination sites on it; ubiquitination databases record sites on it; its protein half-life has been measured; a small molecule that binds it is known.
Target class: Enzyme
Safety:
Unwanted effects reported when the protein is acted on. In parentheses: how it was acted on, where the effect was seen, and who reports it.
Angioedema (source: ClinPGx)
Gene: Protein-coding gene on chromosome 20 (41,136,931 to 41,196,801, forward strand). Ensembl gene ENSG00000124181.
Subcellular location: Cell projection, lamellipodium; Cell projection, ruffle
Subcellular location (Human Protein Atlas): Plasma membrane; Basal body; Cytosol
Pathways (Reactome):
Signal Transduction: Activated NTRK2 signals through PLCG1; Activated NTRK3 signals through PLCG1; DAG and IP3 signaling; Downstream signal transduction; EGFR interacts with phospholipase C-gamma; Erythropoietin activates Phospholipase C gamma (PLCG); PLC-gamma1 signalling; PLCG1 events in ERBB2 signaling; Phospholipase C-mediated cascade: FGFR1; Phospholipase C-mediated cascade; FGFR2; Phospholipase C-mediated cascade; FGFR3; Phospholipase C-mediated cascade; FGFR4; Signaling by ALK; VEGFR2 mediated cell proliferation
Disease: Constitutive Signaling by EGFRvIII; Constitutive Signaling by Ligand-Responsive EGFR Cancer Variants; FCGR3A-mediated IL10 synthesis; Signaling by ALK fusions and activated point mutants; Signaling by ERBB2 ECD mutants; Signaling by ERBB2 KD Mutants; Signaling by ERBB2 TMD/JMD mutants; Signaling by FGFR1 in disease; Signaling by FGFR2 in disease; Signaling by FGFR3 in disease; Signaling by FGFR4 in disease
Immune System: DAP12 signaling; FCERI mediated Ca+2 mobilization; FCERI mediated MAPK activation; Generation of second messenger molecules; ISG15 antiviral mechanism; Role of phospholipids in phagocytosis
Developmental Biology: RET signaling; Role of second messengers in netrin-1 signaling
Hemostasis: PECAM1 interactions
Metabolism: Synthesis of IP3 and IP4 in the cytosol
Gene Ontology:
Molecular function: neurotrophin TRKA receptor binding; phosphatidylinositol-4,5-bisphosphate phospholipase C activity; phospholipase C activity; protein binding; protein kinase binding; guanyl-nucleotide exchange factor activity; phosphatidylinositol phospholipase C activity; calcium ion binding; phosphoric diester hydrolase activity
Biological process: calcium-mediated signaling; cell migration; cellular response to epidermal growth factor stimulus; epidermal growth factor receptor signaling pathway; positive regulation of angiogenesis; positive regulation of blood vessel endothelial cell migration; positive regulation of endothelial cell apoptotic process; positive regulation of epithelial cell migration; positive regulation of release of sequestered calcium ion into cytosol; positive regulation of vascular endothelial cell proliferation; Fc-epsilon receptor signaling pathway; negative regulation of inflammatory response to antigenic stimulus; phosphatidylinositol metabolic process; phosphatidylinositol-mediated signaling; release of sequestered calcium ion into cytosol; T cell receptor signaling pathway; antigen receptor-mediated signaling pathway; intracellular signal transduction; lipid metabolic process; phospholipid catabolic process; signal transduction
Cellular component: COP9 signalosome; cytoplasm; cytosol; lamellipodium; plasma membrane; plasma membrane bounded cell projection; ruffle; ruffle membrane
Genetic constraint (gnomAD): Loss-of-function variants: 67 observed, 162.91 expected, observed/expected ratio (o/e) 0.41, 90% interval 0.34 to 0.5. The upper end of that interval is the gene's LOEUF score, 0.5, which puts it in group 2 of 6, group 1 being the genes least tolerant of losing a copy. Missense variants: 1,234 observed, 1,645.2 expected, observed/expected ratio (o/e) 0.75, 90% interval 0.71 to 0.79. Synonymous variants: 633 observed, 627.17 expected, observed/expected ratio (o/e) 1.01, 90% interval 0.94 to 1.08.
Gene-disease validity (ClinGen):
ClinGen rates the evidence that PLCG1 causes each of these diseases.
immune dysregulation, autoimmunity, and autoinflammation (autosomal dominant): Moderate.
Cancer hallmarks: invasion and metastasis (promotes); proliferative signalling (promotes); escaping programmed cell death (promotes); angiogenesis (promotes)
Homologues: Orthologues: chimpanzee PLCG1 (99% identical), macaque PLCG1 (99% identical), dog PLCG1 (98% identical), pig PLCG1 (98% identical), mouse Plcg1 (97% identical), rat Plcg1 (96% identical), rabbit PLCG1 (95% identical), guinea pig PLCG1 (91% identical), tropical clawed frog plcg1 (81% identical), zebrafish plcg1 (61% identical), Drosophila melanogaster sl (41% identical), Caenorhabditis elegans plc-3 (32% identical), and 3 more. Paralogues in human: PLCG2 (49% identical), PLCH1 (23% identical), PLCH2 (23% identical), PLCE1 (20% identical), PLCL2 (20% identical), PLCB3 (20% identical), PLCD3 (20% identical), PLCD1 (19% identical), PLCB2 (19% identical), PLCB4 (19% identical), PLCD4 (19% identical), PLCL1 (19% identical), and 2 more.
Diseases named in the same sentence as PLCG1 in open-access papers:
PLCG1 is named in the same sentence as 137 diseases in open-access papers, as found by Europe PMC text mining. Sharing a sentence is not in itself a finding about the gene and the disease. The quoted sentences say what the papers report.
breast carcinoma (29 papers, 2004 to 2025). "Inhibition of phosphorylation of PLCγ1 (tyrosine 771) has been shown to reduce the risk of brain metastasis in experimental breast cancer." (PMID 36982207, 2023). "PLCγ1 phosphorylation status was shown to be a prognostic marker of metastatic risk in patients with breast cancer." (PMID 36982207, 2023). "In human, using tumour cases as training and validation sets, we have shown that overexpression of activated PLCγ1 is a risk factor for distant relapse in T1-T2, N0 breast cancer patients undergoing adjuvant chemotherapy." (PMID 31362705, 2019). "However, PLCγ1 is overexpressed and mutated in various cancers including breast cancer, gastric cancer, colorectal cancer, T-cell lymphoma, and AML." (PMID 35574218, 2022). "Recently, PLCγ1 inhibition has emerged as a therapeutic target for hematologic cancers and PLCγ1 phosphorylation status is a biomarker for metastatic risk in luminal breast cancer." (PMID 35574218, 2022). "Phospholipase Cγ1 (PLCγ1) was also associated to metastatic risk in breast cancer patients." (PMID 31922096, 2019). "Although the mechanisms involved remain to be defined, the activation of PLCγ1 as assessed by immunohistochemistry is a strong prognostic factor that can discriminate between high-risk and low-risk patients with hormone-receptor-positive early breast cancers." (PMID 31362705, 2019). "Higher expression of PLCγ1 and its activated forms in tumour samples, was associated with a higher frequency of distant metastasis, highlighting how PLCγ1 not only could be a potential therapeutic target, but also a prognostic marker for metastatic risk in breast cancer patients." (PMID 31922096, 2019). "PLCG1 has emerged as a possible driver for cell proliferation, and increased expression levels of PLCG1 have been observed in breast cancer, colon cancer, and squamous cell carcinoma." (PMID 40862571, 2025). "TSA decreased the transcript and protein levels of aromatase CYP19 and phospholipase C gamma-1 (PLC-γ1) in MCF-7 breast cancer cells." (PMID 36969235, 2023). "Some studies have revealed that PLCG1 can drive the progression of cancers, such as breast carcinoma, colorectal carcinoma, and small-cell lung cancer." (PMID 35677632, 2022). "In breast cancer, it was determined that hsa-miR-200bc/429 cluster directly targets PLCG1 and regulates EGF-driven invasion." (PMID 37533517, 2022). "Our previous studies reported that both stable and inducible PLCγ1 down-regulation can inhibit formation of breast-cancer-derived experimental lung metastasis." (PMID 31362705, 2019). "Conversely, the down-regulation of PLCγ1 expression in breast cancer cells results in decreased lung metastasis formation in mice." (PMID 31362705, 2019). "In the present retrospective study, we analysed the prognostic role of PLCγ1 in early breast cancer patients stratified according to the St." (PMID 31362705, 2019). "PLCγ1 overexpression is a strong predictive surrogate marker of development of metastases in early Luminal-A and -B breast cancer patients, being able to discriminate patients with high and low risk of metastases." (PMID 31362705, 2019). "Downregulation of PLCγ1 has been shown to inhibit human breast cancer cell-derived lung metastasis and progression in mice." (PMID 29464031, 2018). "Our results identify PLCβ1 as an alternative path of cofilin activation in breast cancer—distinct from the route of activation previously ascribed to PLCγ1." (PMID 26620550, 2016). "Together these data support a role for HGF/C-MET/PLCγ-1 route as a direct mediator in breast cancer progression, thus making it a good target for therapeutic intervention." (PMID 25162020, 2014). "SOCS7 loss has resulted in the amplification of HGF/C-MET growth and migrational signalling in the two studied breast cancer cell lines, but pharmacological blockade of PLCγ-1 enzymatic activity has mitigated this amplified signalling." (PMID 25162020, 2014).
breast carcinoma (continued). "Further reports showed that HGF/C-MET downstream intermediate phospholipase Cγ-1 (PLCγ-1) overexpression was also observed in breast cancer, and specific PLCγ-1 inhibition was found to block breast cancer invasiveness." (PMID 25162020, 2014). "In particular we demonstrated that PI3K-mediated PLCγ1 activation is required for epidermal growth factor-induced migration of breast cancer cells." (PMID 20011604, 2009). "PLCγ1 is highly expressed in various tumours, including breast cancers." (PMID 31362705, 2019). "Therefore, in the present study, we investigated the prognostic role of PLCγ1 in these early breast cancer patients stratified according to the St." (PMID 31362705, 2019). "We previously observed a selective nuclear positivity for PLCγ1-pY1253 and PLCγ1-pY783 in patients with early breast cancer, indicating that the nuclear signalling of these activated forms of PLCγ1 may have a specific tumorigenic role." (PMID 31362705, 2019). "Further, high expression of PLCγ1 and its constitutively activated forms (i.e., PLCγ1-pY1253, PLCγ1-pY783) is associated with worse clinical outcome in terms of incidence of distant metastases, but not of local relapse in T1-T2, N0 breast cancer patients." (PMID 31362705, 2019). "Its family member PLCG1 has been identified to be overexpressed in metastatic breast cancers." (PMID 26620550, 2016). "More recently, we reported that PLCγ1 is required for breast cancer cells migration and invasion." (PMID 20011604, 2009). "PIK3R1 and PLCG1 are involved in intracellular signaling cascades and their differential regulation is known to be involved in tumorigenesis, while POU2F1 interacts with several known breast cancer-associated proteins (i.e. BRCA1, BARD1 and PARP1)." (PMID 17280605, 2007). "Furthermore, CASP8 (2%), NLRC4 (1%), NLRP3 (1%), NLRP2 (1%), PLCG1 (1%), NLRP1 (1%), NLRP7 (1%), SCAF11 (1%), GSDMC (1%), and NOD1 (1%) occurred somatic mutations as well as most of them had high frequencies of CNV in breast cancer." (PMID 34589498, 2021). "Since we have reported that the PI3K-dependent activation of PLCγ1 is a key event in migration of breast cancer cells and PLCγ1 is necessary for breast cancer migration and invasion, we investigated whether this novel PI3K/PLCγ1 pathway was involved in the FGF-2-dependent migration of HUVEC." (PMID 20011604, 2009). "Here, we identify an alternate mechanism utilized by metastatic breast cancer cells to activate cofilin in the absence of EGF stimulation induced PLCγ1 activation, increasing the potential pathways for inducing metastatic migration." (PMID 26620550, 2016). "Here, we report our observations of the effect of knocking down SOCS7 gene on the behaviour of breast cancer cells both in vitro and in vivo and to elucidate whether this involves HGF/C-MET pathway using the PLCγ-1 blocker U73122." (PMID 25162020, 2014). "It suggests that the PLCγ1 pathway is not involved in the effect on these breast cancer cells by knockdown of PTPRM." (PMID 23185569, 2012). "For example, STAT3 contributes to colorectal tumorigenesis through interaction with PLCγ1; the combined activation of PLCγ and MAPK is required for FGFR3-induced epithelial to mesenchymal transition (EMT); and FGF induces G2/M transition via the Akt/PLCγ1 axis in MDA-MB-231 breast cancer cells." (PMID 26811493, 2016). "Therefore, this PLCγ1-dependent anticipatory activation of the UPR defines a new role for oestrogens that can create a supportive environment for cancer cell proliferation and resistance to therapy, and might represent a new target in breast cancer." (PMID 31362705, 2019). "On the other hand, we did not detect impairment of Ser473 Akt phosphorylation in breast cancer cells stimulated with epidermal growth factor upon downregulation of PLCγ1 suggesting that the role of PLCγ1 in mediating Akt phosphorylation may be cell and stimulus specific." (PMID 20011604, 2009).
angiosarcoma (21 papers, 2015 to 2025). A malignant tumor arising from the endothelial cells of the blood vessels. "PLCG1 is frequently mutated in angiosarcoma, increasing resistance to apoptosis and the invasiveness of endothelial cells." (PMID 35053609, 2022). "Recent studies demonstrated that the PTPRB and PLCG1 genes involved in angiogenesis were mutated in angiosarcomas." (PMID 33509230, 2021). "Both types of signalling connectivity are relevant for pathology; for example, in angiosarcoma, mutations in PLCγ1 are mutually exclusive with the activating mutations in the upstream RTK." (PMID 31918402, 2020). "The mutated residues that belong to this mechanistic class include PLCγ1 S345, E1163, D1165, and S520 reported in T-cell lymphoma, with the PLCγ1 S345F mutation also found in angiosarcoma." (PMID 31918402, 2020). "Specifically, the somatic mutations in PLCG1 gene have been linked to angiosarcoma and T-cell lymphomas while somatic mutations in PLCG2 contribute to drug (Ibrutinib) resistance in chronic lymphocytic leukaemia (CLL)." (PMID 31918402, 2020). "In mesenchymal tumors, R707Q mutation constitutively activates PLCγ1 and promotes evasion of apoptosis, migration, and invasiveness in angiosarcomas." (PMID 28212550, 2017). "Recurrent driver mutations have been identified in the PTPRB or PLCG1 gene in 38% angiosarcoma patients, including primary and secondary tumors, which reinforce therapeutic efforts to target angiogenesis signaling in angiosarcoma." (PMID 27531900, 2016). "Recurrent mutations in PLCG1 R707Q in angiosarcomas were confirmed in a subsequent study (3 of 10 tumors, 30%)." (PMID 26440310, 2015). "The clinical usefulness of PLCG1 mutational status as a possible predictive biomarker in angiosarcomas in the context of vascular-specific receptor tyrosine kinases directed therapies warrants further study." (PMID 26474454, 2015). "Somatic mutations in PLCG1 have been reported in angiosarcoma." (PMID 37371495, 2023). "Furthermore, we extended our assessment of the hotspot mutations discovered in angiosarcoma to a physiologically relevant endothelial cell line where activation of PLCγ1 occurs in the context of RTK signalling." (PMID 31918402, 2020). "In addition, PLCG1-R707Q missense mutation has been confirmed as a recurrent oncogenic event in angiosarcomas in another study." (PMID 26474454, 2015). "PLCγ1 mutant plays a role in angiosarcoma by promoting invasiveness and influencing angiogenesis through vascular endothelial growth factor (VEGF) signaling." (PMID 37371495, 2023). "Canine spontaneous hemangiosarcoma is a useful model for angiosarcoma both in their histologies and common driver mutations, including NRAS, PLCG1, PIK3CA, and TP5321." (PMID 36658200, 2023). "In angiosarcomas, the most frequently mutated genes in all three cohorts were KDR, PIK3CA, and NF1, followed by KMT2D, NRAS, and PLCG1, which were among the top 10 genes in two of the three cohorts." (PMID 37568749, 2023). "In a separate study, mutations in angiogenesis-related genes were identified in 38% (15/39) of angiosarcoma tumour samples, including recurrent mutations in vascular endothelial-phosphotyrosine phosphatase (VE-PTP) and phospholipase gamma 1 (PLCG1)." (PMID 29250195, 2017). "A recent study analyzed 39 angiosarcomas by whole-genome, whole-exome and targeted sequencing and revealed recurrent mutations in PTPRB and PLCG1, both linked with angiogenesis." (PMID 26474454, 2015). "We identified a number of known genetic alterations in angiosarcomas, including MYC and KLT4 amplifications, RAS mutations, inactivating PTPRB mutations and an activating PLCG1 mutation." (PMID 26440310, 2015).
angiosarcoma (continued). "In this study we provide another example of a different mechanism; a frequent PLCγ1 R707Q substitution found in angiosarcoma decreases stability of the cSH2 domain and in this indirect way could affect the autoinhibition." (PMID 31918402, 2020). "More recently, whole exome sequencing of primary and secondary angiosarcoma demonstrated mutations in the endothelial phosphatase, Protein tyrosine phosphatase, receptor type, B (PTPRB) and Phospholipase C, gamma 1 (PLCG1), a signal transducer of tyrosine kinase activators." (PMID 28056866, 2017). "The pathogenesis of angiosarcoma is probably also related to other genes, including CIC gene rearrangement, increased expression of the MYC gene and FLT-4 gene, and mutations of PTPRB and PLCG1, but the present study focused on the PD-1/PD-L1 and PI3K/mTOR signaling pathways." (PMID 34397726, 2021). "This heterogeneity in clinical behaviour might be related to the high genetic variability described in angiosarcomas, with several genes abnormalities identified in B-AS patients such as CIC, PLCG1, KDR and MYC." (PMID 32616718, 2020).